SNX32 (sorting nexin 32)
Description:
Involved in endosomal trafficking of cargo proteins, including transferrin-bound transferrin receptor (TFRC), cation-independent mannose-6-phosphate receptor (IGF2R) and epidermal growth factor receptor (EGFR). Functions redundantly with other BAR domain-containing sorting nexins in endosome to trans-Golgi network transport of IGF2R. Regulates in coordination with SNX5 sorting and trafficking of EGF-activated EGFR to multivesicular bodies for lysosomal degradation. Plays an essential role in neurite outgrowth, controlling basigin/EMMPRIN (BSG) trafficking to the cell surface (By similarity).
Synonyms: SNX6B; FLJ30934
Tractability: Antibody: its Gene Ontology location is reachable by antibodies, with high confidence. PROTAC: ubiquitination databases record sites on it; its protein half-life has been measured.
Gene: Protein-coding gene on chromosome 11 (65,833,834 to 65,856,896, forward strand). Ensembl gene ENSG00000172803.
Subcellular location: Cell membrane; Early endosome; Golgi apparatus, trans-Golgi network; Recycling endosome; Late endosome
Subcellular location (Human Protein Atlas): Cytosol; Focal adhesion sites
Gene Ontology:
Molecular function: protein binding; phosphatidylinositol binding
Biological process: endosomal transport; endosome to lysosome transport via multivesicular body sorting pathway; neuron projection extension; regulation of macroautophagy; retrograde transport, endosome to Golgi; intercellular transport
Cellular component: early endosome; late endosome; plasma membrane; recycling endosome; retromer, tubulation complex; trans-Golgi network; endosome; cytosol; Golgi apparatus
Genetic constraint (gnomAD): Loss-of-function variants: 58 observed, 58.59 expected, observed/expected ratio (o/e) 0.99, 90% interval 0.8 to 1.23. The upper end of that interval is the gene's LOEUF score, 1.23, which puts it in group 5 of 6, group 1 being the genes least tolerant of losing a copy. Missense variants: 589 observed, 556.54 expected, observed/expected ratio (o/e) 1.06, 90% interval 0.99 to 1.13. Synonymous variants: 262 observed, 228.19 expected, observed/expected ratio (o/e) 1.15, 90% interval 1.04 to 1.27.
Homologues: Orthologues: chimpanzee SNX32 (98% identical), macaque SNX32 (94% identical), dog SNX32 (93% identical), mouse Snx32 (91% identical), rat Snx32 (89% identical), pig SNX32 (86% identical), Drosophila melanogaster Snx6 (53% identical), Caenorhabditis elegans snx-6 (48% identical), Drosophila melanogaster Snx1 (20% identical), Caenorhabditis elegans snx-1 (17% identical), zebrafish si:dkey-28n18.9 (15% identical), Drosophila melanogaster SH3PX1 (14% identical), and 1 more. Paralogues in human: SNX6 (68% identical), SNX5 (61% identical), SNX1 (21% identical), SNX2 (20% identical), SNX4 (17% identical), SNX7 (17% identical), SNX9 (17% identical), SNX30 (17% identical), SNX18 (16% identical), SNX8 (16% identical), SNX33 (13% identical), SNX11 (10% identical), and 3 more.
Diseases named in the same sentence as SNX32 in open-access papers:
SNX32 is named in the same sentence as 4 diseases in open-access papers, as found by Europe PMC text mining. Sharing a sentence is not in itself a finding about the gene and the disease. The quoted sentences say what the papers report.
Alzheimer disease (1 paper, 2020). A progressive, neurodegenerative disease characterized by loss of function and death of nerve cells in several areas of the brain leading to loss of cognitive function such as memory and language. "Our findings suggest that genes such as SNX32, which was initially associated with increased risk of Alzheimer disease, may potentially influence other complex traits in the opposite direction." (PMID 32413284, 2020).
cancer (1 paper, 2021). A tumor composed of atypical neoplastic, often pleomorphic cells that invade other tissues. "Many of the genes such as JHY, PLAAT1, PNMA8B, RPL37P6, SNX32, UGGT2 and Y_RNA have not been related to any cancer, yet." (PMID 33672117, 2021).
tumor (1 paper, 2022). "The expression of SNX32 was high in both the tumor and paracarcinoma tissues." (PMID 36035311, 2022).
SNX32 also shares sentences with these, for which no sentence is quoted: rosacea (1 paper).